CYP17A1 (cytochrome P450 family 17 subfamily A member 1)
Diseases named in the same sentence as CYP17A1 in open-access papers (continued):
Sharing a sentence is not in itself a finding about the gene and the disease.
Obesity (12 papers, 2008 to 2026). Accumulation of substantial excess body fat. "We also monitored the body weight of CYP17A1-deficient rats fed a high-fat diet since prior research had shown that mice with this gene defect have an obesity-related phenotype." (PMID 41385510, 2025). "Further pathway enrichment and network analyses revealed a substantial effect of Cyp17a1 genotype on associated cardiovascular and obesity-related pathways involving aspartate and L-arginine." (PMID 34070975, 2021). "The Cyp17A1 heterozygous mice were backcrossed to the commonly used atherogenic ApoE (Apolipoprotein E) deficient genetic background to induce atherosclerosis and obesity when feeding a Western-type diet (WTD)." (PMID 34070975, 2021). "We have provided evidence that CYP17A1 is associated with obesity and atherosclerosis in our previous study, but the relationship between CYP17A1 and the gut microbiota remains unclear." (PMID 34070975, 2021). "We have previously shown an association of Cyp17a1 KO with obesity in female mice." (PMID 34070975, 2021). "Therefore, in the present study, we aimed to determine the effect of diet and Cyp17a1-deficiency on the gut microbiota and to relate the findings to the obesity phenotype in these mice." (PMID 34070975, 2021). "Furthermore, some research findings indicate that obesity develops from a mutation in the Cyp17a1 gene; however, the exact mechanism underlying obesity and the impact of obesity on metabolic syndrome resulting from Cyp17a1 gene mutation remains unknown." (PMID 41385510, 2025). "ADSCs were cultured from fat samples to investigate the etiology of obesity in the Cyp17a1 KO group." (PMID 41385510, 2025). "In this study, we investigated the effects of Cyp17a1 gene knockout (KO) on obesity and metabolic syndrome." (PMID 41385510, 2025). "As in previous results, Cyp17a1 homozygous knockout (-/-) rats showed signs of obesity, including a particular rise in SAT and adipose tissue hypertrophy." (PMID 41385510, 2025). "Previous studies have demonstrated that CYP17A1 knockout mice develop obesity and metabolic disorders." (PMID 41140715, 2025). "This study explored the role of the Cyp17a1 gene in obesity and its subsequent impact on metabolic diseases using a KO rat model, which was generated for the first time by CRISPR-Cas9." (PMID 41385510, 2025). "In this context, we bred Cyp17a1-deficient mice on an atherogenic ApoE KO genetic background to study the role of this gene and a WTD on lipid metabolism and obesity." (PMID 34070975, 2021). "In our recent study, we showed that CYP17A1 is associated with an obesity and atherosclerosis phenotype, but the influence of CYP17A1 on the gut bacteria and the consequences of such interaction for obesity were unclear." (PMID 34070975, 2021). "Cytochrome P450, family 17, subfamily A, polypeptide 1 (Cyp17A1), a member of the CYP450 family, is implicated in cholesterol, steroids and other lipid responses, and their relationship with obesity has been previously reported." (PMID 31060494, 2019). "All these results remained virtually unchanged when additionally adjusted for body weight, indicating that the CYP17A1 locus impacts BP independently of obesity." (PMID 25692033, 2015). "Our results remained virtually unchanged when adjusted, or not adjusted, for body weight, indicating that the CYP17A1 locus impacts BP independently of obesity." (PMID 25692033, 2015). "Changes in steroid hormone levels may be involved in the healthy obesity trait observed in Cyp17a1 KO rats." (PMID 41385510, 2025). "Therefore, the goal of this research was to find out how the Cyp17a1 gene alters adipose tissue metabolism and how this influences the development of obesity and the resulting metabolic syndrome." (PMID 41385510, 2025). "Despite causing obesity-induced hyperglycemia, the Cyp17a1 gene knockout did not affect insulin secretion or responsiveness." (PMID 41385510, 2025).
Obesity (continued). "The impact of NT5C2 rs11191580 polymorphism on infants' obesity may function through the region of linkage disequilibrium of several genes (NT5C2, CYP17A1, and CNNM2)." (PMID 35295960, 2022). "However and due to the interesting obesity phenotype in XX Cyp17a1 KO, we tried to determine the level of E1–3 in remaining plasma material in XX Cyp17a1 KO mice on an Apoe genetic background and under chow diet." (PMID 32472014, 2020). "Thus, there is strong evidence for the role of CYP17A1 in obesity and fat deposition." (PMID 34070975, 2021). "The DEGs Cyp17a1, Cfd and Saa1 were the ones that interacted with obesity-related genes in the interaction network, on the basis of which we speculated that these genes may be related to obesity." (PMID 31060494, 2019). "Cyp17a1 KO in rats using CRISPR-Cas9 resulted in sex dimorphism and obesity, and interestingly, site-specific accumulation was found in subcutaneous adipose tissue (SAT)." (PMID 41385510, 2025). "Transcripts for several candidate genes for obesity were absent in the whole brain or absent in specific regions of the brain (Cyp17a1, Gdf15, Gpr151, Lmx1b, Olig3, Sbk1, Sim1, Skor1, Tnni3k)." (PMID 39920851, 2025). "We found that despite of obesity induced by Cyp17a1 gene knockout, metabolic syndrome did not appear, and that Cyp17a1 gene knockout affected distinct metabolic shifts, underscoring its potential role in modulating disease progression in metabolic syndrome." (PMID 41385510, 2025). "In conclusion, this study demonstrated that Cyp17a1 deletion in rats via CRISPR-Cas9 induced obesity but did not lead to metabolic syndrome." (PMID 41385510, 2025). "However, further studies are needed to clarify the role of the aspartate/L-arginine axis in obesity and body fat distribution, and in particular, to determine whether oral supplementation with either L-arginine or aspartate may reduce fat deposition in the Cyp17a1 KO mouse model." (PMID 34070975, 2021). "In conclusion, in the Cyp17a1 KO rat models we generated for the first time, the phenotype promoted by obesity reflected metabolically healthy obesity hypothesis, but this did not exhibit metabolic syndrome-like features due to enhanced metabolism in the SAT." (PMID 41385510, 2025).
Adrenal insufficiency (10 papers, 2013 to 2025). Insufficient production of steroid hormones (primarily cortisol) by the adrenal glands. "The identification of a CYP17A1 variant causing 17OHD in another patient with proximal hypospadias had compelled additional investigations for adrenal function, and adrenal insufficiency was subsequently diagnosed." (PMID 39936125, 2025). "Adrenal insufficiency induced by abiraterone acetate is a rare but serious adverse event that arises due to the drug’s inhibition of CYP17A1, which leads to a reduction in cortisol production." (PMID 40136360, 2025). "Mutations in genes related to steroid biosynthesis (such as CYP11A1, CYP17A1, HSD3B2, HSD17B3, and StAR) will lead to androgen synthesis disorders with adrenal insufficiency besides the SRD5A2 gene mutation which results in the insufficient transformation of dihydrotestosterone from testosterone." (PMID 40247401, 2025).
Hyperinsulinemia (9 papers, 2017 to 2026). An increased concentration of insulin in the blood. "This localised anomaly interacts with hyperinsulinemia to enhance ovarian CYP17A1 activity by stimulating the ERK1/2–SF1 pathway independently of PI3K." (PMID 41010046, 2025). "At the systemic level, modified extracellular vesicle cargo results in hyperinsulinemia, exacerbating androgen excess via elevating CYP17A1 and diminishing aromatase in the ovary." (PMID 41010046, 2025). "Hyperinsulinemia increases the expression of steroidogenic enzymes, such as cytochrome P450c17 (CYP17A1), in theca cells." (PMID 40234859, 2025). "The ovarian theca cells are the primary source of androgen excess, driven by the intrinsic enzymatic hyperactivity of steroidogenic enzymes, such as cytochrome P450 family 17 subfamily A member 1 (CYP17A1), and augmented by hyperinsulinemia and elevated LH levels." (PMID 41155686, 2025). "Chronic hyperinsulinemia diminishes the production of hepatic SHBG and increases androgen levels via activating CYP17A1 in theca cells through insulin stimulation." (PMID 41596408, 2026).
mineralocorticoid excess (9 papers, 2014 to 2025). "CYP17A1 variants impair cytochrome P450 17α-hydroxylase (P450c17) enzyme expression in the adrenal gland and gonads, resulting in cortisol and sex steroid deficiency, in combination with mineralocorticoid excess." (PMID 37316894, 2023).
prostate tumor (9 papers, 2012 to 2024). "Abiraterone is a CYP17A1 inhibitor that blocks the synthesis of androgens in prostate tumor cells, the testes, and adrenal glands." (PMID 26220655, 2015). "Abiraterone acetate is an androgen biosynthesis inhibitor, which can highly specifically and irreversibly bind to the rate limiting enzymes CYP17A1, C17 lyase, and C20 lyase for androgen synthesis, thereby inhibiting the androgen synthesis in testicular, adrenal, and prostate tumors." (PMID 39280891, 2022).
endometriosis (8 papers, 2013 to 2025). The growth of functional endometrial tissue in anatomic sites outside the uterine body. "Between these groups, we were able to observe a significant upregulation of CYP17A1 mRNA expression in endometrial biopsies of endometriosis patients with severe pain symptoms compared to healthy controls." (PMID 41154581, 2025). "This is in contrast with the literature, where it is reported that CYP17A1 is equally expressed in endometriosis patients compared to controls, however, there is no data available regarding patients’ pain symptoms." (PMID 41154581, 2025). "Polymorphisms in CYP17A1, a key enzyme in estrogen biosynthesis, and COMT, which regulates the metabolism of catechol estrogens, have been linked to altered local estrogen homeostasis and increased susceptibility to endometriosis." (PMID 41462999, 2025). "Interestingly, our results showed that mRNA expression of CYP17A1 is significantly upregulated in eutopic endometrial biopsies from endometriosis patients with severe pain symptoms when compared to healthy controls." (PMID 41154581, 2025). "Next, we assessed whether the expression levels of CYP11A1 and CYP17A1 in the endometriosis lesion correlates with the concentrations in the peritoneal fluid of the respective neurosteroids they produce (i.e., PS and DHEAS)." (PMID 41154581, 2025). "A few studies reported detectable levels of the enzymes involved in the generation of DHEA from cholesterol (StAR, CYP11A1 and CYP17A1) in endometriosis, suggesting that, in contrast to eutopic endometrium, endometriosis is able to produce steroids from cholesterol." (PMID 30283331, 2018).
autism (6 papers, 2015 to 2025). Persistent deficits in social interaction and communication and interaction as well as a markedly restricted repertoire of activity and interest as well as repetitive patterns of behavior. "Evidence pointing toward the importance of such enzymes was previously found via genetic associations between autism and single-nucleotide polymorphisms in CYP17A1, CYP19A1, and CYP11B1 genes." (PMID 31075898, 2019). "Prior evidence pointing toward the importance of such enzymes was previously found via genetic associations between autism and single-nucleotide polymorphisms in CYP17A1, CYP19A1 and CYP11B1 genes." (PMID 24888361, 2015). "A CYP17A1 deficiency can be used as a mirror image concerning the alterations of steroid hormones while enhancing our understanding of the role in affected subjects with autism." (PMID 35743898, 2022). "A recent systematic review and metanalysis from a respectable number of 321 boys and 64 girls with autism indicated that 17/20 Lyase activity is altered in boys as well as girls, implying a relevant role of CYP17A1." (PMID 35743898, 2022). "The aim of this study was to analyze potential alterations of the activity of CYP17A1 in affected boys and girls with autism versus healthy controls." (PMID 35743898, 2022). "When searching for potential treatment options in autism, pharmaceuticals directly addressing CYP17A1 activity—especially 17/20 Lyase activity—should be considered as therapeutical targets." (PMID 35743898, 2022). "A genetic study of autism found evidence that single nucleotide polymorphisms in sex steroid synthesis genes (ESR2, CYP11B1, CYP17A1, CYP19A1) were associated with autism traits and autism without intellectual disability and good verbal skills." (PMID 30570672, 2019). "Furthermore, a direct association was performed between autism and RORA as a novel candidate gene in autism, directly implying a role of Cytochrome P450 17A1 (CYP17A1; also P450c17 and P450sccII)." (PMID 35743898, 2022). "Maybe in further studies it might be interesting to correlate the severity of the autism with CYP17A1 activity and to develop a cut-off of alteration, as this would allow one to implement a rational pharmacotherapy." (PMID 35743898, 2022). "As, recently, increased CYP17A1 activity has been suggested, the stronger routing towards androgens is further implied in line with our findings of lower progesterone concentrations in boys and girls with autism than healthy controls." (PMID 35888093, 2022). "However, as glucocorticoid as well as androgen metabolites showed higher values in subjects affected with autism as compared to healthy controls, the data indicate, despite higher CYP17A1 activity, the presence of increased substrate availability in line with the Cholesterol theory of autism." (PMID 35743898, 2022). "As previously indicated by us and others, a dysregulation with a general dysregulation not solely of CYP17A1, but in general (not only androgens), is most conspicuous in boys and girls with autism." (PMID 35743898, 2022). "As this is a hypothesis with potential for falsification, it shall be stated that CYP17A1 activity is not altered in children with autism versus healthy controls." (PMID 35743898, 2022).
coronary artery disease (6 papers, 2013 to 2025). "CYP17A1 genetic variants are associated with coronary artery disease, myocardial infarction and visceral and subcutaneous fat distribution; however, the underlying pathological mechanisms remain unknown." (PMID 32472014, 2020). "Moreover, a gene in the steroidogenesis pathway (CYP17A1) is reliably associated with coronary artery disease." (PMID 23597181, 2013).
ovarian carcinoma (6 papers, 2009 to 2025). A malignant neoplasm originating from the surface ovarian epithelium. "However, in a recent study, the genetic variant of CYP17A1 (rs743572) showed a significant association with ovarian cancer risk." (PMID 38001897, 2023).
colorectal cancer (5 papers, 2007 to 2025). A primary or metastatic malignant neoplasm that affects the colon or rectum. "We also observed a significant interaction between rs17724534 and rs10883782 in the CYP17A1 gene on colorectal cancer risk." (PMID 21627810, 2011). "We found that the combined effects of rs10883782 and rs17724534 in CYP17A1 were significantly associated with colorectal cancer risk (empirical p value = 0.04)." (PMID 21627810, 2011). "We observed a weak association between the CYP17A1 rs17724534 SNP and colorectal cancer risk (OR per risk allele (A) = 1.39, 95% CI = 1.09-1.78, corrected p-value = 0.07)." (PMID 21627810, 2011). "Our findings offer some support for a suggestive association of CYP17A1 and CYP19A1 variants with colorectal cancer risk." (PMID 21627810, 2011). "In addition, a suggestive interaction between rs17724534 and rs10883782 in 2 discrete LD blocks of CYP17A1 was observed in relation to colorectal cancer (empirical p value = 0.04)." (PMID 21627810, 2011).
Hyperglycemia (5 papers, 2021 to 2025). An increased concentration of glucose in the blood. "Together with the earlier OGTT results, these data suggest that the reason Cyp17a1 KO female’s blood sugar levels were higher was not due to an issue with insulin secretion, but rather due to hyperglycemia, which caused the blood sugar to be elevated overall." (PMID 41385510, 2025).
hypospadias (5 papers, 2019 to 2024). Hypospadias is the displacement of the urethral meatus on the ventrum of the penis. "Apart from the clear effects of CYP17A1 mutations and total CYP17A1 deficiency in men with missing or partial external genitalia development, milder variants of testicular CYP17A1 deficiency have been associated to idiopathic infertility and hypospadias." (PMID 35455061, 2022). "As far as we know, the association between maternal CYP1A1/CYP17A1 SNPs and hypospadias have not been reported in Chinese population, let alone gene-environment interaction." (PMID 30858503, 2019). "The pathogenesis of hypospadias is viewed as multifactorial, and induced by genes polymorphisms and gene-environment interactions, hence, it is necessary to investigate the roles of interaction between CYP1A1/CYP17A1 polymorphisms and environmental risk factors." (PMID 30858503, 2019). "Moreover, three studies found that key enzymes involved in testosterone synthesis, represented by Cyp11a1, Cyp17a1, Hsd3b, Scarb1, Star, Hsd17b3 and Srd5α2, were significantly reduced at the genetic level in DBP- or DEHP-induced hypospadias male fetal rats." (PMID 39698037, 2024).
metabolic syndrome (5 papers, 2020 to 2025). A cluster of metabolic risk factors for CARDIOVASCULAR DISEASES and TYPE 2 DIABETES MELLITUS. "This shows that CYP17A1 deficiency cannot be considered to lead to a metabolic syndrome." (PMID 41385510, 2025). "Considering that cardiometabolic risk factors that form the metabolic syndrome are interrelated, the CYP17A1 SNPs may also be associated with elevated fasting blood glucose and the presence of dyslipidemia, but this hypothesis is yet to be tested." (PMID 34484290, 2021). "First, to examine if sexual maturation differs in metabolic syndrome between Cyp17a1 KO rats and wild-type rats, we conducted an insulin tolerance test on chow-diet-fed rats at 5, 12, and 20 weeks old." (PMID 41385510, 2025). "The positive correlation of seen Cyp17a1 gene and body weight in the present study may imply that Cyp17a1 can contribute to the development of metabolic syndrome." (PMID 32489392, 2020). "Based on these previous findings, the present study investigated whether common genetic variants at both CYP17A1 and SERPINA6/A1 loci are associated with the metabolic syndrome, its related cardiometabolic risk factors, and circulating glucocorticoids, in black South Africans." (PMID 34484290, 2021). "Furthermore, Cyp17a1 KO rats did not exhibit the rise in plasma insulin concentration that is frequently seen in patients with metabolic syndrome, even when they were given a high-fat diet." (PMID 41385510, 2025).
adrenocortical carcinoma (4 papers, 2016 to 2022). "Effects of genistein and daidzein on steroid metabolism were determined in vitro, in HEK293 cells expressing CYP17A1 and in the human adrenocortical carcinoma H295R cell model." (PMID 31031706, 2019).